INS (insulin)
Diseases named in the same sentence as INS in open-access papers (continued):
Sharing a sentence is not in itself a finding about the gene and the disease.
Obesity (continued). "Celastrol treatment mitigates obesity-induced metabolic dysfunctions by enhancing insulin sensitivity in skeletal muscle via upregulation of GLUT4, improvement of mitochondrial function, and activation of antioxidant defense mechanisms." (PMID 40894926, 2025). "The prevalence of uterine cancer is commonly observed in conjunction with obesity and metabolic disorders, and obesity drives uterine cancer by increasing the estrogen and insulin levels." (PMID 40718420, 2025). "To ascertain the bioactive components in RFE that exhibited anti-obesity effects and improved insulin sensitivity, we performed LC-MS and HPLC analyses." (PMID 40076460, 2025). "Both factors are vital in the development of obesity, as their dysregulation can lead to excessive fat accumulation, impaired insulin sensitivity, and metabolic disturbances." (PMID 41306340, 2025). "Thirdly, it has been demonstrated that increased concentration of adiponectin reverses β-cell damage and impaired insulin secretion in obesity-related T2DM." (PMID 39812542, 2025). "IL-1β, another pro-inflammatory cytokine elevated in obesity, further contributes to the impairment of insulin signaling." (PMID 40282189, 2025). "This cephalic-phase insulin secretion was shown to be impaired in individuals with obesity as well as in mice fed a high-fat diet." (PMID 39496966, 2025). "Elimination of senescent cell populations through targeted molecular approaches improves glucose homeostasis and insulin action in experimental obesity models." (PMID 40630101, 2025). "Administration of FGF19 to obese mice or its overexpression has been reported to increase metabolic rate and improve obesity, hepatic steatosis, insulin sensitivity and plasma lipid levels." (PMID 39944202, 2025). "Considerable evidence indicates that the amount of thermogenic beige adipocytes within subcutaneous WAT (sWAT) depots corresponds with insulin sensitivity and protection against the comorbidities of obesity and aging." (PMID 41206127, 2025). "This chronic, low-grade inflammation, termed metabolic inflammation, disrupts insulin signaling in key tissues, resulting in systemic insulin resistance, a central feature of obesity and metabolic syndrome." (PMID 40183584, 2025). "While glycemic control and the progression of complications can be effectively managed in HNF4A-MODY patients receiving long-term insulin therapy, the potential risks of hypoglycemic episodes, obesity, and atherosclerosis remain significant concerns." (PMID 40589512, 2025). "One such study performed in muscle biopsies of individuals with obesity collected before and after sleeve gastrectomy or gastric bypass surgery assessed the temporal dynamics in insulin sensitivity, transcriptome, and DNA methylome changes following surgery." (PMID 40862085, 2025). "Insulin resistance (IR), a central feature of obesity-related metabolic dysregulation, manifests as reduced insulin responsiveness in adipose, hepatic, and muscle tissues, ultimately leading to β-cell failure and T2DM onset." (PMID 41341586, 2025). "A higher prevalence of vaginal infections was found in the diet-treated mothers (p < 0.05), while insulin-treated mothers had a higher prevalence of pregnancy-induced hypertension, pregnancy-induced hypothyroidism and obesity (p < 0.05)." (PMID 39796611, 2025). "The insulin sensitivity and anti-obesity effects of quercetin, baicalein, and kaempferol, which are the main components of almond skin, were investigated." (PMID 41303557, 2025). "These FFA increase significantly in obesity and are responsible for increasing AT in response to an alteration of the antilipolytic effect of insulin and less re-esterification of FFA by adipocytes in obesity." (PMID 40076851, 2025). "The relationship between obesity and a reduction in insulin-mediated glucose uptake has been well-established for more than 3 decades." (PMID 40108925, 2025).
Obesity (continued). "LPS is thought to initiate SOCS3 expression, disrupting leptin and insulin signaling in the brain and further paralleling obesity-related mechanisms." (PMID 41515969, 2025). "The heart loses its metabolic flexibility in obesity and/or T2D, driven in part by cardiac insulin resistance, resulting in an increased reliance on fatty acid oxidation for ATP production and a corresponding decrease in cardiac glucose oxidation." (PMID 40663803, 2025). "In male mice, obesity induced by HF-HSD administration was associated with higher plasma glucose, insulin, monocyte chemoattractant protein-1 (MCP-1), and vascular cell adhesion molecule 1 (VCAM-1), but not IL-6 concentrations." (PMID 39861371, 2025). "The results showed that 15-keto-PGE2 protected against diet-induced obesity and markedly improved both glucose tolerance and insulin sensitivity in HFHSD-fed mice." (PMID 40119175, 2025). "Another strength of this study lies in its integrative approach, combining histological, molecular, and metabolic assessments to elucidate how distinct dietary protein sources modulate adipose tissue function and insulin sensitivity in obesity." (PMID 41156477, 2025). "Studies have observed a rise in the Clostridiales order, known for its efficient SCFA production, across various infection models, highlighting the potential of SCFAs in modifying obesity and enhancing insulin sensitivity." (PMID 41268546, 2025). "The DKA episode occurred in a female patient with T1D and obesity, who was taking canagliflozin since > 12 months with concomitant reduction in insulin doses by almost 50%." (PMID 40347422, 2025). "The metabolic indicators of children with obesity, such as blood glucose and insulin, were also monitored simultaneously." (PMID 40150457, 2025). "In our study, RFP deficiency improved metabolic disorders in HFD-induced obesity models by downregulating PPAR-γ target genes, leading to reduced fat accumulation and improved insulin sensitivity." (PMID 40968148, 2025). "In obesity and diabetes, this coordination breaks down: insulin-resistant adipose tissue releases fatty acids even when fed, and the heart becomes fat-reliant, impairing metabolic flexibility." (PMID 41470890, 2025). "Clinical studies have explored the use of FMT as a potential treatment for obesity, with one study showing enhanced insulin sensitivity and decreased body weight in obese individuals with metabolic syndrome transplanted from lean donors." (PMID 40295195, 2025). "Diets rich in bioactive compounds, particularly the Mediterranean diet, have been demonstrated to be strongly associated with improvements in metabolic health, reduced rates of obesity, and enhanced insulin sensitivity." (PMID 40002389, 2025). "Yakuts exhibited higher scores for β-cell dysfunction, hyper-insulin secretion, and lipid metabolism alterations, whereas Chechens and Tatars had higher scores for obesity-related mechanisms." (PMID 41001674, 2025). "Research into insulin’s role in protein and lipid metabolism is vital for understanding its contribution to energy homeostasis and obesity-related conditions." (PMID 40725728, 2025). "Another clinical study involving patients with obesity who have sedentary lifestyles demonstrated improved brain insulin action, cognitive benefits, and improved hippocampal function following an 8-week exercise program." (PMID 41294899, 2025). "In obesity, chronic inflammation disrupts insulin signaling due to elevated levels of pro-inflammatory cytokines." (PMID 40282189, 2025). "Older adults with obesity are more likely to transition to a metabolically unhealthy state due to age-related metabolic changes, such as increased insulin resistance and inflammation." (PMID 40807115, 2025). "The MD has emerged as a powerful tool in managing and preventing both obesity and T2D, demonstrating consistent benefits for glycemic control, insulin sensitivity, and weight management." (PMID 40697264, 2025).
Obesity (continued). "Butyrate, for example, is known to enhance insulin sensitivity and has protective effects against obesity-related inflammation." (PMID 39997751, 2025). "In obesity, skeletal muscle becomes insulin resistant with decreased IRS1 and Glucose Transporter protein type 4 (GLUT4), contributing to systemic hyperinsulinemia." (PMID 40868103, 2025). "These gaps directly motivate the present systematic review and meta-analysis, which aims to examine the acute effects of exercise-snack interventions on postprandial glucose and insulin metabolism in adults with obesity." (PMID 41356824, 2025). "RBP4 is recognized as a negative acute inflammatory reactant and as a novel adipokine, whose levels increase in insulin-resistant conditions, such as obesity, metabolic syndrome, type 2 diabetes mellitus, as well as cardiovascular diseases." (PMID 41227378, 2025). "Arai C., Miyake M., Matsumoto Y., Mizote A., Yoshizane C., HanayaY., Koide K., Yamada M., Hanaya T., Arai S., Fukuda S. Trehaloseprevents adipocyte hypertrophy and mitigates insulin resistancein mice with established obesity." (PMID 41164278, 2025). "It exhibits significant anti-obesity effects in rodents and humans, for example regulating body weight, improving blood glucose and lipid metabolism, reducing insulin resistance." (PMID 40384781, 2025). "More recent research indicates that let-7d-5p presence regulates insulin signaling targets, correlates to increased obesity, and induces microglial release of inflammatory cytokines." (PMID 40869172, 2025). "The present findings indicate that 'Meein' extract demonstrates therapeutic promise in obesity management and enhancement of insulin sensitivity in T2D." (PMID 40895680, 2025). "This analysis evaluated the potential reciprocal relationships between the TNF-α -308 G/A gene polymorphism, the Composite Dietary Antioxidant Index (CDAI), and insulin-related variables in Spanish adults with obesity." (PMID 40732969, 2025). "Higher early pregnancy blood pressure and fasting insulin levels were detected in women with obesity at 2‐year postpartum assessment, while only the fasting insulin level was higher in women with obesity at 5–6 years." (PMID 41229166, 2025). "As Nrf2 acts as a sensor for pro-oxidant stress, it is activated to reduce the harmful effects of ROS and improve insulin sensitivity, exhibiting anti-obesity effects." (PMID 39859121, 2025). "Treatment with synthetic TRβ agonists KB-141 in ob/ob mice improves glucose tolerance and insulin sensitivity in a dose-dependent manner, supporting the potential of selective TRβ activation for anti-obesity, lipid-lowering, and antidiabetic therapy." (PMID 41438090, 2025). "Another interesting study in muscle-specific BDNF knockout mice showed that ingesting a high-fat diet exacerbated the development of obesity, insulin resistance, intramyocellular lipid deposition and mitochondrial dysfunction." (PMID 39857710, 2025). "A marked elevation was seen in individuals with moderate obesity (BMI 30.0–34.9), whose median insulin level reached 97.7 μU/mL (IQR: 70.0 to 222.7 μU/mL)." (PMID 40868057, 2025). "Physical activity is an essential part of any weight loss program not only because it increases energy expenditure and reduces insulin resistance, but it is a key factor for the prevention of metabolic adaptation typical of patients with obesity." (PMID 38778593, 2025). "Liver glycogen levels and gluconeogenesis are coordinately regulated in insulin-resistant people with obesity." (PMID 40454488, 2025). "Obesity-induced systemic or local inflammation and insulin resistance transform the adipose tissue secretome from an anti-inflammatory to a pro-inflammatory state." (PMID 39857433, 2025). "Obesity and immunometabolic depression also share metabolic disturbances (e.g., increased leptin and insulin and reduced adiponectin)." (PMID 41375608, 2025).
Obesity (continued). "ACACB knockout increased insulin sensitivity, mitigated high-fat-diet-induced obesity risks, and ameliorated hyperglycemia in mice." (PMID 40004488, 2025). "T2D mainly results from progressively impaired insulin secretion by β-cells in the context of pre-existing liver, skeletal muscle, and adipose tissue IR, often a consequence of obesity." (PMID 40006091, 2025). "Its upregulation has been linked to lipid-induced stress via the TGFβ-SMAD3 signaling pathway, and its dysregulation has been observed in insulin-resistant conditions such as polycystic ovary syndrome and obesity." (PMID 41385529, 2025). "In reaction to obesity, adipose tissue macrophages release more miR-155, which targets PPARγ and inhibits insulin signaling in muscle cells, hepatocytes, and adipocytes." (PMID 40565979, 2025). "Obesity-related dysbiosis also impairs mucosal immune defenses and disrupts gastric barrier function, while chronic low-grade inflammation and insulin resistance further weaken host immunity." (PMID 41323605, 2025). "For example, mice with XX chromosomes have up to a two-fold increase in obesity, weight gain, elevated lipid and insulin levels, and fatty liver when fed a high-fat diet (HFD)." (PMID 40299427, 2025). "During obesity, visceral adiposity impairs insulin signaling, contributing to insulin resistance (IR) and the development of metabolic syndrome." (PMID 40872520, 2025). "Hypertrophy of adipocytes induces mechanical stress to neighboring cells and insufficient vascularization/hypoxia and promotes chronic inflammation and fibrosis, leading to unhealthy obesity, such as exacerbation of insulin insensitivity and dyslipidemia." (PMID 40424271, 2025). "ALA's effects on insulin sensitivity and secretion further underscore its utility in managing diabetic polyneuropathy, polycystic ovary syndrome and obesity." (PMID 40207422, 2025). "Glucagon-like peptide-1 analogues (GLP-1As) are now well-established and widely used agents for the treatment of obesity, and they have demonstrated superior efficacy compared to insulin and metformin in the management of T2DM." (PMID 41149695, 2025). "Dietary supplementation with low-fermentable fiber enhanced the ability of FMT to improve insulin sensitivity in patients with concomitant obesity and metabolic disorders." (PMID 40564077, 2025). "Studies have shown that 4-HIL promotes weight loss, reduces fatty liver, and optimizes lipid profiles in the context of obesity, while also improving insulin sensitivity and lowering blood glucose levels in diabetes." (PMID 40917356, 2025). "These strategies assist in reducing BMI, improving insulin sensitivity, and decreasing inflammatory markers, leading to a general improvement of metabolic health and possibly preventing obesity-related comorbidities." (PMID 40431370, 2025). "The reason for the decrease in the concentration of BCAAs in the postoperative period is related to the improvement of insulin resistance and the restoration of insulin’s ability to inhibit protein hydrolysis in patients with obesity after gastrectomy." (PMID 40933259, 2025). "Studies have demonstrated that EBN supplementation improves glucose metabolism and insulin sensitivity in obesity-induced insulin-resistant rats and mice, menopause-induced insulin-resistant rats, type 1 diabetic rats, and type 2 diabetic mice." (PMID 40429763, 2025). "This sex-specific EPO regulation of fat mass is due to the protective effect of estrogen on obesity in female mice that contributes to energy metabolism, insulin sensitivity, and lipid metabolism." (PMID 39996752, 2025). "Studies suggest that the KD not only helps patients with obesity or diabetes lose weight but also aids in increasing insulin sensitivity in type 2 diabetes patients and improves blood sugar control." (PMID 40535039, 2025). "β-carotene can upregulate adiponectin, which is suppressed in obesity and is known for its insulin-sensitizing, anti-inflammatory, and anti-atherogenic effects." (PMID 40143179, 2025).
Obesity (continued). "Previous reports have indicated that celastrol exerts anti-obesity effects by enhancing leptin sensitization, decreasing food intake, and restoring glucose tolerance and insulin sensitivity." (PMID 40500724, 2025). "In experimental research, diet-induced obesity models that simulate a Westernized dietary pattern in murine models are widely used to investigate mechanisms of weight gain and disruptions in insulin, lipid, and glucose metabolism." (PMID 40573106, 2025). "One study reports decreased peripheral insulin sensitivity after seven-day oral vancomycin use in males with obesity and metabolic syndrome." (PMID 41243448, 2025). "Activation of Car in mice has been shown to mitigate hepatic steatosis, increase glucose tolerance and insulin sensitivity, and reduce obesity under metabolic and nutritional stress." (PMID 39915454, 2025). "The present study revealed the anti-inflammatory, anti-obesity, and insulin-sensitizing effects of BR extract." (PMID 39942605, 2025). "GHR-KO pigs reflect the phenotype of increased insulin sensitivity despite obesity observed in human LS patients." (PMID 41125144, 2025). "IR is defined by a reduced cellular response to insulin, serving as a key contributor to the development of the metabolic syndrome, obesity, and cardiovascular diseases." (PMID 40072058, 2025). "Freinkel proposed that excessive circulating maternal glucose crossing the placenta provides energy to the fetus, while stimulating insulin secretion from fetal β-cell, ultimately leading to excessive fetal growth and obesity." (PMID 40375950, 2025). "Taken together, Ins-G5b–KOs subjected to diet-induced obesity show reduced glucose-induced insulin secretion in vitro and in vivo, and glucose tolerance is impaired." (PMID 40906536, 2025). "Individuals with obesity exhibit elevated basal and postprandial plasma insulin levels, primarily due to an increased secretion rate from beta cells." (PMID 41210503, 2025). "Taken together, our data suggest that the interplay among insulin clearance, action, and secretion plays a pivotal role in glucose homeostasis in youth with obesity." (PMID 40470991, 2025). "In women with obesity and type 2 diabetes, insulin and leptin levels are elevated, creating a hormonal environment that can promote cancer cell growth by promoting the activation of insulin-like growth factor 1 (IGF-1)." (PMID 40431387, 2025). "When basal insulin is required, a combination with GLP1RAs should be preferred over basal insulin alone in people with T2D and obesity." (PMID 41212412, 2025). "In obesity, plasmalogen modulation found to reduce body weight, improve insulin sensitivity, and lower plasma lipid levels." (PMID 40245986, 2025). "TPH2 mRNA levels of subcutaneous adipose tissue showed a positive linear correlation with fasting plasma AST and plasma insulin levels in humans, suggesting that obesity-induced hyperinsulinemia increases TPH2 expression in human adipose tissues." (PMID 40455408, 2025). "The functional diversity of these adipocyte populations underlies their capacity to buffer circulating lipids and modulate insulin sensitivity, processes that are compromised in obesity and T2DM." (PMID 41002965, 2025). "In preclinical models of high fat diet induced obesity there are several studies that show MSC administration improved insulin sensitivity, decreased triglyceride levels and lipotoxicity." (PMID 40770765, 2025). "In particular, ectopic lipid accumulation due to obesity induces lipotoxicity, which elevates the secretion of free fatty acids and reactive oxygen species (ROS), impairing insulin signaling and sensitivity." (PMID 40076460, 2025). "Conversely, lipids known for their insulin-sensitizing and antiinflammatory properties, such as FAHFAs, were significantly lower in individuals with obesity." (PMID 40548377, 2025).